TMEM176B (transmembrane protein 176B)
Diseases named in the same sentence as TMEM176B in open-access papers (continued):
Sharing a sentence is not in itself a finding about the gene and the disease.
tumor (continued). "Similarly, analysis of the CPTAC database revealed a consistent reduction in TMEM176B protein levels in OC tumor tissues compared to normal tissues." (PMID 40108613, 2025). "The frequent silencing of TMEM176B in OC tissues suggested that this gene may be a tumor suppressor." (PMID 40108613, 2025). "Moreover, significant differences in TMEM176B protein expression were observed across various tumor stages, tumor grades, and patient age groups according to the CPTAC database." (PMID 40108613, 2025). "Furthermore, according to the CPTAC database, significant differences in TMEM176B protein expression were observed across various tumor stages, tumor grades, and patient age groups." (PMID 40108613, 2025). "Furthermore, TMEM176B knockout or the pharmacologic inhibition of TMEM176B demonstrates that it suppresses tumour growth through CD8+ T cells by triggering the activation of inflammasomes." (PMID 39001509, 2024). "The overexpression of TMEM176B significantly increased tumour growth in both PC9TMEM176Boe (506.96 ± 115.15 mm3, n = 10/10 vs. 97.13 ± 21.78 mm3, n = 10/10) and A549TMEM176Boe (187.67 ± 39.91 mm3, n = 9/10 vs. 90.94 ± 41.99 mm3, n = 8/10) cells compared to the empty vector controls." (PMID 39001509, 2024). "A recent paper reported that myeloid TMEM176B is a potential modulator of tumor immunotherapy." (PMID 37308559, 2023). "By isolating CD11b+CD14+CD163+ macrophages from normal, peritumor, and intratumor tissues and performing RNA sequencing, we found that macrophage TMEM176B expression levels were lower in normal tissue but higher in tumor tissue, inversely correlating with the expression of CD146." (PMID 37308559, 2023). "Interestingly, CD146 was involved in the NLRP3 inflammasome-mediated activation of macrophages in the tumor microenvironment, partially by inhibiting transmembrane protein 176B (TMEM176B), an immunoregulatory cation channel." (PMID 37308559, 2023). "To test whether CD146+ macrophages controlled tumor development through TMEM176B in vivo, we established a tumor model in M-WT and M-KO mice, followed by treatment with BayK8644." (PMID 37308559, 2023). "Furthermore, the TMEM176B inhibitor BayK8644 controlled tumor growth in a Tmem176b, Casp1/11 and CD8-dependent manner." (PMID 36340035, 2022). "The expression of TMEM176B is up-regulated in the tumor blood vessels of human renal cell carcinoma specimens, suggesting that it is implicated in tumor angiogenesis and could be a target of anti-angiogenesis therapy for cancer patients." (PMID 35399535, 2022). "The study has reported that targeting TMEM176B controls tumor growth." (PMID 35399535, 2022). "It is the possible reason for the larger tumor size in Tmem176b knockout mice." (PMID 35399535, 2022). "Targeting TMEM176B may not only enhance the anti-tumor immune response to immune checkpoint inhibitors, but may also directly inhibit tumor cell growth." (PMID 34943938, 2021). "The result of the functional analysis suggested that several intracellular functions that might be involved in the cell proliferation, migration, and tumor growth are regulated by TMEM176B." (PMID 34943938, 2021). "Similarly, elevated protein levels of TMEM176B are detected in multiple malignancies, moreover, inhibition of TMEM176B has already been proved to promote CD8+ T cell-mediated tumor growth control, enhancing the therapeutic efficacy of cancers." (PMID 32780768, 2020). "Finally, we identify BayK8644 as a potent TMEM176B inhibitor that promotes CD8+ T cell-mediated tumor control and reinforces the antitumor activity of both anti-CTLA-4 and anti-PD-1 antibodies." (PMID 31085177, 2019). "Thus, Tmem176b deletion enhances CTL-mediated tumor control through mechanisms involving the caspase-1/IL-1β pathway." (PMID 31085177, 2019). "Notably, a growing body of research supports the notion that TMEM176B might be instrumental in tumor initiation and progression." (PMID 40108613, 2025).
tumor (continued). "Furthermore, we found the regulatory effect of TMEM176B on tumor-infiltrating CD8+ T cells." (PMID 35399535, 2022). "Also, TMEM176B was positively linked to immune cell infiltration in SKCM, which may explain that TMEM176B affects the prognosis of tumor patients." (PMID 35399535, 2022). "In order to further clarify whether ITGB5 is a proto-oncogene and whether TIMP1 and TMEM176B are tumor suppressor genes, we used dCas9-KRAB-mediated CRISPRi technology to knock down the expression of ITGB5, and used dCas9-VPR-mediated CRISPRa technology to activate TIMP1 and TMEM176B expression." (PMID 34109215, 2021). "To further clarify whether knockdown of ITGB5 and activation of TIMP1 and TMEM176B expression affect tumor cell invasion, we used dCas9-KRAB-mediated CRISPRi to knock down ITGB5 expression, and used dCas9-VPR-mediated CRISPRa to activate TIMP1 and TMEM176B expression." (PMID 34109215, 2021). "Moreover, in vitro re-stimulation of TDLN cells with ovalbumin (OVA) showed increased proportion of IL-17+ CD4+ T cells in Tmem176b−/− compared with WT mice, and in vivo IL-17A blockade showed a clear trend toward suppression of the antitumor effect in tumor-bearing Tmem176b−/− mice." (PMID 31085177, 2019). "Thus, TMEM176B-dependent immune inhibitory mechanisms may operate within the tumor microenvironment and TDLN." (PMID 31085177, 2019). "ISOQ inhibited both platelet aggregation and Factor Xa generation induced by tumor cells and significantly suppressed tumor growth, thromboinflammatory markers, and expression of tissue factor, VEGF, TMEM176B, and PD‐L1." (PMID 41474368, 2026). "In MMRd tumors, resistance following anti-PD-1 treatment is driven by the expression of TIM3, LAG3, CTLA4, and TIGIT by TILs, as well as tumor clonal selection and the expression of TREM2, CSF1R, IFITM, TMEM176B and IL1B by myeloid cells." (PMID 40027748, 2025). "We then performed univariate and multivariate Cox regression analyses incorporating sex, age, tumor location and size, GC cell invasion depth, lymph node metastasis, differentiation grade, TNM staging, and TMEM176B expression." (PMID 38438907, 2024). "For instance, TMEM176B has been shown to inhibit the activation of the NLRP3 inflammasome, linking adaptive and innate anti-tumor responses." (PMID 39170226, 2024). "In our study, we found up-regulated expression of TMEM176A and TMEM176B both in malignant cells and myeloid cells, which might negatively affect the differentiation of DC cells leading to the potential imbalance of antigen presentation and promoting tumor immune escape." (PMID 37265785, 2023). "Overall, the downregulation of CD146 in TAMs promotes the activation of JNK signaling, thereby upregulating the expression of TMEM176B and MDSC recruitment-related chemokines, which in turn accelerate tumor development." (PMID 37308559, 2023). "In the study, we found that, in comparison to wild-type animals, Tmem176b knockout lowered the expression of IFN-γ, PRF1 and GZMB in TIL CD8+ T cells, indicating that the function of tumor-infiltrating T cells was suppressed." (PMID 35399535, 2022). "We explored the expression of TMEM176B in SKCM and its relationship with tumor patients’ prognosis and immune infiltration." (PMID 35399535, 2022). "According to the tumor grades, in TCGA database, compared with WHO II and III, the transcription levels of MS4A4A, MS4A4E, MS4A6A, MS4A7, TMEM176A, and TMEM176B were the highest in WHO IV." (PMID 35734424, 2022). "Our findings revealed that the proportion of CD3+ CD8+ T cells in Tumor-infiltrating T lymphocytes (TILS), is dramatically reduced after Tmem176b knockout, the same trend can be seen in CD3+ CD4+ T cells." (PMID 35399535, 2022). "We would like to further study the regulatory relationship between TMEM176B and CD8+ T cells in the tumor microenvironment (TME)." (PMID 35399535, 2022).
tumor (continued). "We constructed a mouse tumor model to figure out how Tmem176b regulates the differentiation, function, and immune infiltration levels of CD8+ T cells in the tumor microenvironment." (PMID 35399535, 2022). "In addition to suppressing TMEM176B and PD‐L1, ISOQ markedly reduced expression of key angiogenic and pro‐inflammatory mediators in tumor lysates." (PMID 41474368, 2026). "When used in combination, ISOQ and ZAF achieved cooperative enzymatic inhibition in vitro and elicited superior antitumor efficacy in vivo, reducing tumor volume and suppressing tissue factor, VEGF, TMEM176B, and PD‐L1 more effectively than high‐dose monotherapy." (PMID 41474368, 2026). "Our results revealed that, compared with the negative control, the overexpression of TMEM176B in A2780 cells led to a significant decrease in tumor mass and volume." (PMID 40108613, 2025). "Diminishing TMEM176B expression has been found to impede cell proliferation and migration in MDA-MB-231 cells, further affirming that decreased TMEM176B expression suppresses tumour growth in vivo." (PMID 39001509, 2024). "A χ2 test demonstrated significant positive correlations among TMEM176B expression and tumor size, GC cell invasion depth, lymph node metastasis, differentiation grade, and clinical staging (p < 0.05)." (PMID 38438907, 2024). "The immunohistochemical analysis of tissue arrays demonstrated enhanced TMEM176B staining in tumour tissues as opposed to their corresponding adjacent normal tissues." (PMID 39001509, 2024). "Since CD146+ macrophages play an important role in tumor prevention and because the deletion of CD146 on macrophages upregulates the expression of TMEM176B, to further improve the antitumor effect of AA98, we combined a TMEM176B inhibitor and AA98 in tumor therapy." (PMID 37308559, 2023). "Therefore, the impact of TMEM176B on CD8+ T cell infiltration level and the prognosis of tumor patients deserves close attention." (PMID 35399535, 2022). "Our findings showed that after tumor implantation, knocking down Tmem176b has effect on T cell activation rather than anti-apoptosis, or proliferation." (PMID 35399535, 2022). "The influence of Tmem176b on the differentiation of T cells was not significant in other non-tumor organs." (PMID 35399535, 2022). "However, the percentage of total CD8+ T cells within tumor infiltrates, as well as the absolute number of total and tumor-specific CD8+ T cells, was considerably increased in tumors grown in Tmem176b−/− mice compared with those developed in WT mice." (PMID 31085177, 2019). "Administration of BayK8644 significantly increased survival of tumor-bearing WT but not Tmem176b−/− mice compared with injection of vehicle control." (PMID 31085177, 2019). "Thus, BayK8644 restrains EG7 tumor growth in a TMEM176B-, caspase-1/11-, and CD8+ T cell-dependent manner, phenocopying Tmem176b−/− mice." (PMID 31085177, 2019). "Presently, there is a absence of research focusing on the role of TMEM176B in tumor cells." (PMID 40108613, 2025). "We then excised the mouse xenograft tumor tissues and found that the phosphorylation rates of the PI3K-Akt-mTOR signaling pathway constituents and the ASNS expression levels were markedly lower in the neoplasms of the TMEM176B knockdown mice than in those of the control mice." (PMID 38438907, 2024). "Therefore, we speculated that TMEM176B was negatively regulated by CD146 and controlled tumor development." (PMID 37308559, 2023). "To study whether increased inflammasome activation could be responsible for tumor control in mice lacking Tmem176b, we blocked IL-1β and studied EG7 tumor development." (PMID 31085177, 2019). "To further clarify whether inhibition of ITGB5 and activation of TIMP1 and TMEM176B affect tumor cell migration, we also used dCas9-KRAB-mediated CRISPRi technology to knock down ITGB5 expression, and used dCas9-VPR-mediated CRISPRa technology to induce TIMP1 and TMEM176B activation." (PMID 34109215, 2021).
tumor (continued). "Furthermore, TMEM176B expression exhibited a significant increase in tumour stages II and III but not in tumour stage I." (PMID 39001509, 2024).
cancer (17 papers, 2019 to 2026). A tumor composed of atypical neoplastic, often pleomorphic cells that invade other tissues. "ITGB5, TIMP1, and TMEM176B can be used as molecular diagnostic targets or therapeutic targets in the future, as their combination is useful for cancer treatment." (PMID 34109215, 2021). "The protein encoded by TMEM176B has also been suggested as a potential biomarker for various cancers." (PMID 32114984, 2020). "Although the transmembrane protein TMEM176B has been linked to a number of cancers, its role in cancer immunity remains unknown." (PMID 35399535, 2022). "The results indicated that the most affected cellular ligand–receptor interactions occurred between cancer cells and endothelial cells, and TMEM176B overexpression enhanced the interaction strength." (PMID 39001509, 2024). "Our research discovered a link between the expression of TMEM176B and the infiltration degree of immunocytes in cancers." (PMID 35399535, 2022). "Cancer cases were separated into high- and low-expression groups based on TMEM176B median expression levels to evaluate how TMEM176B expression influences prognosis of patients in SKCM." (PMID 35399535, 2022). "Overall, our results suggest that the putative ion channel TMEM176B is expressed in cancer cells, and it has important roles in regulating gene expression, as well as cell signaling." (PMID 34943938, 2021). "The chromosome 7q36.1-3 region within which lies the gene for TMEM176B exhibits frequent gain/amplification in a number of human cancers." (PMID 34943938, 2021). "Studies examining the importance of TMEM176B expression in cancer cells have been limited, and reports on its intracellular localization in different cells have been conflicting." (PMID 34943938, 2021). "The results showed that APOE, CTSD, LGALS2, and TMEM176B expression in normal tissues was significantly higher than that in cancer tissues (P < 0.01)." (PMID 34873574, 2021). "Although TMEM176B was described in human lung fibroblasts more than 20 years ago, the understanding of its role in cancer biology remains limited." (PMID 34943938, 2021). "In contrast, the importance of inflammasomes in immune responses against cancers received strong support from studies on an innate immune checkpoint referred to as transmembrane protein 176B (TMEM176B)." (PMID 32027447, 2020). "Moreover, TMEM176A and TMEM176B have been demonstrated to have a role in the regulation of cancer pathology." (PMID 39001509, 2024). "Additionally, we examined the associations of TMEM176B with prognosis and survival, revealing a significant enhancement in TMEM176B expression among patients who died from cancer." (PMID 39001509, 2024). "We demonstrated the expression status of TMEM176B across various types of cancer." (PMID 35399535, 2022). "ITGB5, TIMP1, and TMEM176B are abnormally expressed in several human cancers." (PMID 34109215, 2021). "Overall, much remains to be understood regarding the role of TMEM176B in cancer biology." (PMID 34943938, 2021). "To investigate whether TMEM176B-mediated regulation of inflammasome activation may influence antitumor immunity, we first examined the relevance of TMEM176B expression in human cancer." (PMID 31085177, 2019). "TMEM176A and TMEM176B are unique members of the MS4A family with distinct expression characteristics, and recent studies have improved our understanding of their structures, distribution patterns, biological functions, and associations with various clinical diseases, including cancer." (PMID 39717774, 2024). "Moreover, TMEM176B affects GC cancer progression by regulating asparagine synthetase (ASNS)." (PMID 38438907, 2024). "However, in the high-TMEM176B-expression cancer cells AKT/mTOR pathway, activation could be compensated even under tamoxifen suppression." (PMID 34943938, 2021). "Therefore, the observed downregulation of both, STAB1 and TMEM176B may highlight novel players in the anti-cancer activity of metformin." (PMID 32780768, 2020).
cancer (continued). "While investigating the prognostic potential of cMo IFN in cancer patients, we observed significant overexpression of TMEM176A and TMEM176B genes in cMo IFN from responders, though both genes were differentially expressed even before treatment." (PMID 36263038, 2022). "Among them, ITGB5 is highly expressed cancers, TIMP1, and TMEM176B are lowly expressed in cancers." (PMID 34109215, 2021). "TMEM176B is a member of the membrane spanning 4-domains (MS4) family of transmembrane proteins, and a putative ion channel that is expressed in immune cells and certain cancers." (PMID 34943938, 2021). "We found that ITGB5 promotes cancer, while TIMP1 and TMEM176B suppress cancer." (PMID 34109215, 2021). "In addition, we found significant downregulation of multiple cancer-related genes coding for cytochrome P450 1B1 (CYP1B1), C-C chemokine receptor type 2 (CCR2), stabilin-1 (STAB1) and transmembrane protein 176B (TMEM176B)." (PMID 32780768, 2020). "However, the role of TMEM176B in cancers has yet to be determined, or we do not yet have a complete grasp of its function in malignancies." (PMID 35399535, 2022). "The proliferation of MDA-MB-231 in TMEM176B-overexpressing, but not TMEM176B-silenced, cells was suppressed by the anti-TMEM176B pAb-2573, suggesting that anti-TMEM176B antibodies could have therapeutic anti-cancer effects." (PMID 34943938, 2021).
bacterial infections (1 paper, 2024). "Previous research has indicated that TMEM176B might play a role in modulating immune response during viral and bacterial infections." (PMID 39170226, 2024).
TMEM176B also shares sentences with these, for which no sentence is quoted: colitis (1 paper); cutaneous melanoma (1); dermatitis (1); esophageal cancer (1); experimental autoimmune encephalomyelitis (1); fibrosarcoma (1); fibrosis (1); infection (1); lymphoma (1); ovarian carcinoma (1); pneumonic (1); psoriasis (1); schizophrenia (1); skin inflammation (1); viral infection (1).